GFAP (glial fibrillary acidic protein)
Diseases named in the same sentence as GFAP in open-access papers (continued):
Sharing a sentence is not in itself a finding about the gene and the disease.
glioma (continued). "Moreover, a more differentiated phenotype is observed in glioma stem-like cells exposed to FN1, with decreased levels of SOX2 and increased levels of GFAP, highlighting the importance of FN1 for glioma onset and progression." (PMID 35562862, 2022). "Glioma cell invasion is strongly but not significantly correlated with either astrocyte %GFAP+ (Spearman rs = −0.767, p > 0.05) or microglia %CD68+ (rs = 0.747, p > 0.05)." (PMID 35906273, 2022). "We next examined whether the effects of HDAC6 inhibitors on glioma cilia extend to normal neural cell types that harbor aaTub+ and ARL13B+ cilia, such as radial glial cells and GFAP+ astrocytes." (PMID 33915983, 2021). "FAP+ cells were efficiently propagated in conditions suitable for pericytes, expressed mesenchymal markers PDGFRβ, αSMA, and TE-7, but were negative for glioma (GFAP) and endothelial (vWf) markers." (PMID 34282761, 2021). "Patient-derived glioma cells were characterized by immunofluorescence using Nestin, a neural progenitor marker, SOX2, a marker for pluripotency and self-renewal, and astrocytic marker GFAP confirms cells of glial origin in the culture." (PMID 34489494, 2021). "Histologically, the FGFR3 glioblastomas showed intense GFAP reactivity and various degrees of “FGFR3-TACC3 glioma recurrent morphological features”, in addition to high-grade (HG) features, such as brisk mitotic activity, necrosis and microvascular proliferation." (PMID 33853673, 2021). "receiver operating characteristic-curve analyses of randomly selected patients (33%; N = 82) of various glioma grades and brain metastasis, showed a high accuracy area under the curve of 90% for the percentage CD16+GFAP+ monocytes predicting for a brain lesion." (PMID 33501422, 2021). "The investigators obtained the list of the top 15 important features based on the scores obtained from the chi-squared stats between each non-negative feature and the glioma grade, and S100, GFAP, and Ki 67 expression levels." (PMID 33014836, 2020). "Predictably, the histopathology of GDCX cells in the murine tumor was different from that of the wt-C6 murine glioma tumor; tissues stained with anti-DCX, anti-GFAP, and anti-vimentin antibodies showed a positive correlation with high DCX expression as seen in GDCX tumor." (PMID 32050972, 2020). "Cell morphology and expression analysis of GFAP, Vimentin, verified that TXNDC9 could regulate glioma cell differentiation." (PMID 32897242, 2020). "As opposed to healthy glia cells, glioma generally possess increased amounts of the intermediate filaments vimentin, nestin, and GFAP." (PMID 31003495, 2019). "To confirm that c-JunDN could in fact suppress c-Jun function in U251 cells, we examined the expression of two genes that are regulated by AP-1 transcriptional complexes in astrocytes and glioma cells; SERPINA3 (α1-antichymotrypsin) and GFAP." (PMID 30651087, 2019). "A representative example shows that αDG and EphA3 are expressed predominantly in regions, where mesenchymal tumour elements are present and expression is low or absent on the more differentiated GFAP+ glial tumour element." (PMID 31463571, 2019). "Both in vivo and in vitro studies showed that hydrogen treatment could attenuate the stemness of glioma cells, which was evidenced by the decreased expression of stemness markers (CD133 and Nestin) and the enhanced expression of glia marker GFAP." (PMID 31113492, 2019). "The tumors derived from the glioma primary cell cultures propagated in serum containing media were characteristically well demarcated and GFAP negative." (PMID 29434344, 2018). "Herein, the expression of β3-Tubulin (a neuron-specific marker) and GFAP (a glioma marker) were not changed significantly." (PMID 30305611, 2018). "Cells within these high-grade glioma tumors expressed the astrocytic marker glial fibrillary acidic protein, lacked expression of the neuronal marker NeuN, and displayed high level of the proliferation marker Ki67." (PMID 30456354, 2018).
glioma (continued). "Descriptions of dedifferentiated SMGs, even GFAP-negative or gliomas with neural phenotype, are noted in the literature." (PMID 29805974, 2018). "In glioma patients, a relatively large fraction of the CD9+ exosomes were also GFAP-positive (mean = 25.1%); whereas, a small but detectable fraction (mean = 2.9%) of CD9+ exosomes from control individuals had GFAP on their surface (an 8.7-fold difference)." (PMID 29383115, 2017). "Moreover, the astrocytic marker, glial fibrillary acidic protein (GFAP), cannot fully discriminate between glioma progenitors and further differentiated glioma cells." (PMID 29113105, 2017). "Immunofluorescence staining for nestin was negative, but immunofluorescence staining for GFAP was strongly positive, and β-tubulin staining was positive, indicating that glioma stem cells had differentiated." (PMID 28955297, 2017). "Finally, levels of GFAP and HiF-1α are highly correlated, generating a R2 value of 0.48 (p = 0.0006) in GBM and 0.35 (p = 0.0053) in all glioma." (PMID 26689994, 2016). "Our attempts to identify cell types expressing a nuclear Cx43 signal revealed that it was not present in cells harboring characteristics of glioma cells such as GFAP (marker of astrocytic cells) or Ki67 (marker of proliferative cells)." (PMID 27306693, 2016). "Western blot analysis also detected the astrocyte-specific marker GFAP in C6 glioma cell lysates but not in IMG cell lysates." (PMID 26819091, 2016). "IHC staining revealed SR-A1 co-localization with macrophages/microglia (Iba-1+), but not glioma cells (GFAP+) in human gliomas." (PMID 27367025, 2016). "Malignant astrocytic tumours are GFAP negative, and numerous high-grade gliomas appear to have lower GFAP expression." (PMID 27494894, 2016). "The mouse conditional knock-in models with mutant IDH1 induced in Nestin-expressing cells were reported to die directly after birth, while the analogous GFAP-induced models survived slightly longer, but did not develop gliomas during their lifespan." (PMID 27145078, 2016). "Other markers, including S-100, CD1a, glial fibrillary acidic protein (GFAP), oligo-2, CD21, CD23, CD35, CD30, CD20, Melan-A and HMB45, were all negative, which excluded Langerhans cell histocytisis (LCH), glioma, lymphoma, and follicular dendritic cell sarcoma, and so on." (PMID 27535029, 2016). "Our report confirms previous reports that spinal meningiomas can be intramedullary and that GFAP positivity is not specific for glial tumors." (PMID 26155457, 2015). "Tumor cells were negative for epithelial membrane antigen (EMA) and glial fibrillary acidic protein (GFAP) which effectively ruled out a meningioma or a glial neoplasm." (PMID 26294993, 2015). "Not GFAP, but GFAP autoantibodies were very recently demonstrated to be a useful serum marker for glioma patients, possibly due to the fact that blood brain barrier (otherwise impermeable for antibodies) is altered in advanced or aggressive disease." (PMID 25298751, 2014). "In these studies, transposon mobilization in the GFAP compartment failed to generate gliomas with substantial penetrance, even in a p19Arf heterozygous background." (PMID 25423036, 2014). "Analysis revealed strong immunostaining of the GFAP marker in HFA and glioma cell cultures, while AA cultures showed very weak GFAP expression in the majority of cultures (data not shown)." (PMID 25415278, 2014). "The PNETs were more sharply demarcated from adjacent brain than the glial tumours, had no vascular endothelial proliferation or pseudopalisading necrosis and were immunonegative for GFAP." (PMID 25047029, 2014). "Twelve major discriminators between low- and high-grade gliomas were identified: HCD2, HBA and HBD were up-regulated in high-grade gliomas, whereas expression levels of CRYAB_b, IPYR, TPIS, PEA15, PSD13, GFAP, IDH3A, 6PGL and PHP14 were found to be higher in low-grade than in high-grade tumors." (PMID 25050814, 2014).
glioma (continued). "Virally transduced expression of active Ras and Akt induces glioma formation from nestin-expressing neural progenitors but not from GFAP-expressing astrocytes in mice." (PMID 23424671, 2013). "Upon examination of the brain at the time of euthanasia no macroscopic abnormalities were found, however, in GFAP-Cre/RictorloxP/loxP animals histological examination revealed bilateral, multifocal infiltrating glioma with nearly complete penetrance." (PMID 23077666, 2012). "More significantly, the GTI did not identify GFAP, a known differentiation marker for normal cells of astroglial origin as well as a glioma marker, which ranked highly using COPA." (PMID 21365010, 2011). "GFAP‐/colligin 2‐positive cells were never found in glioma tissue and they were very rarely present in the glioma blood vessels." (PMID 19067716, 2010). "In this study, we investigated the expression of multiple cell surface markers characteristic of glial genesis hierarchy in freshly isolated viable glioma cells as well as the expression of GFAP, NSE and synaptophysin in the fixed specimens from a cohort of low-grade and high-grade glioma patients." (PMID 18398462, 2008). "GFAP expression was detected, as anticipated, in all low- and high-grade gliomas analyzed, but the expression of NSE and synaptophysin was only detected in high-grade gliomas." (PMID 18398462, 2008). "The expression of GFAP and these oligodendrocyte progenitor surface markers suggests that along the oligodendrocyte lineage differentiation hierarchy, A2B5+/PDGFRα+ glioma cells were compromised in differentiation downstream of A2B5/O4, but upstream of the O1 stage." (PMID 18398462, 2008). "Notably, increased serum GFAP concentration after surgical resection occur regardless of glioma grade, confirming its low specificity for tumor burden." (PMID 41399659, 2026). "In GSLCs and glioma tissues, Sohlh1 expression was negatively correlated with the expression of GSLC markers, such as Nestin, CD133, CD44, SOX2 and OCT4, whereas Sohlh1 expression was positively correlated with the expression of GSLC differentiation markers, such as MAP2, GFAP and MBP." (PMID 40418209, 2025). "Moreover, both senescent glioma cells (identified with GFAP, γ-H2AX, and P21 positive, and Lamin B1 negative expression) and TAMs (identified with IBA1, γ-H2AX, and P21 positive, and Lamin B1 negative expression) were reduced by GDC-0879." (PMID 40781221, 2025). "Immunostaining showed that CELSR2 was positive in GFAP-positive astrocytes of both CP-H122 and U87 MG cell lines, but a rare detectable CELSR2-positive signal was found in the CELSR2-shRNA treated U87 MG cell lines and CELSR2-shRNA treated Grade 3 primary glioma cells." (PMID 41184253, 2025). "There are also limitations: Although GFAP is a robust glioma marker, it does not label all glioma subpopulations (e.g., GFAP-negative tumor cells), and future work could incorporate additional markers (e.g., Sox2, Olig2)." (PMID 41226489, 2025). "Menin is also highly expressed in the cytoplasm of glioma cells, where it interacts with the type III intermediate filament proteins glial fibrillary acidic protein (GFAP) and vimentin, suggesting that menin may also promote migration and metastasis of glioma cells." (PMID 39336822, 2024). "We hypothesized that high-grade gliomas may coexist with high FAP and GFAP expression." (PMID 39629119, 2024). "However, the GFAP-KI mice had a much shorter lifespan than their controls and did not develop glioma." (PMID 36765553, 2023). "For example, GFAP may be negative in gliomas of non-astrocyte origin but positive in high-grade gliomas with admixture of differentiated astrocytic cells." (PMID 36831736, 2023).
glioma (continued). "Overall, our results indicate that GFAP and a handful of other proteins could be valuable non-invasive biomarkers for glioma, but additional validation studies are needed." (PMID 36959545, 2023). "When we analyzed the connection between glioma cells in more detail, we frequently observed GFAP-rich intercellular bridges containing mitochondria that were detached from the substrate and in contact with GFAP-negative cells with a spherical closed structure." (PMID 37886397, 2023). "However, the expression level of NCAPG in glioma was not correlated with the sex of the patient or the expression levels of Ki-67 and GFAP." (PMID 35372056, 2022). "Some other biomarkers are regarded as the common glioma protein targets, such as Ki67, S100 and GFAP, which may not be solid." (PMID 34831392, 2021). "Also, flow cytometric analysis of glioma patients’ blood revealed a small population of GFAP+ intermediate monocytes and GFAP+ non-classical monocytes, while relatively very limited GFAP+ classical monocytes were found in the blood of healthy controls." (PMID 33501422, 2021). "Previous study showed that the HSV-TK gene driven by human GFAP promoter could selectively kill glioma cell lines, but did not investigated the possible ability of neural differentiation under GCV treatment." (PMID 34370752, 2021). "In normal CTX, protoplasmic astrocytes were seen in close apposition to homogeneously built vessels whereas GBM cases showed gemistocytic glioma cells coopting the external walls of disrupted vessels where anomalous, not easily discernible GFAP-expressing astrocytic-like structures were recognized." (PMID 33579378, 2021). "There was no change in infiltrating GFAP-positive astrocytes surrounding glioma-filled fibres." (PMID 32390004, 2020). "Thus, they isolated glioma stem lines growing as floating neurosphere-like aggregates (positive for SOX2 and differentiating to GFAP-positive cells) and other ones growing as irregularly-shaped floating aggregates, with some adherent cells (positive for CD44 and negative for SOX2)." (PMID 30279357, 2018). "The transfected glioma cells grown in differentiated (DMEM with 10% FBS allows to maintain mixture of cells with various lineage) and stem cell conditions (NSA media supplemented with N2, B27, EGFFR and FGF) were stained using CD133, NESTIN, GFAP and OLIG2 markers." (PMID 27517625, 2017). "Finally, using human malignant glioma stem cells (OB1 cell line), we showed that CTGF treatment induced GFAP, CD133, Nestin and inhibited Sox2 expression, suggesting a possible role for CTGF not only during normal brain development but also in the glioma differentiation program." (PMID 26241738, 2015). "In addition, recruitment of Iba1+ microglia and GFAP+ astrocytes to orthotopically implanted GL261 glioma sites occurred already without virus injection." (PMID 26149494, 2015). "The anti-proliferative activity of ASH-WEX in human and rat glioma cells may be the result of inhibition of proliferation and differentiation of tumor cells as verified by MTT test and enhanced expression of GFAP, a marker of glial cell differentiation." (PMID 20007262, 2011). "Furthermore, the gliomas were found in the Nestin drive tv-a neural progenitors, but not in the differentiated GFAP-tv-a astrocytes, highlighting the importance of both cooperating mutations as well as the differentiation status of the cell of origin." (PMID 21896959, 2011). "The main difference between the GTI and COPA therefore appears to be the successful exclusion of false positive genes such as GFAP, which may be highly expressed in the glioma samples, but do not represent true outliers." (PMID 21365010, 2011). "However, it cannot be excluded that A2B5+CD44+GFAP+ glioma cells without detectable PDGFRα and O4 expression (e.g.: case #9) actually represent the expansion of ARP-like cells." (PMID 18398462, 2008).
glioma (continued). "Furthermore, the absence of DR5 in GFAP positive astroglial cells is linked to the expression of BNIP3, a transcriptional inhibitor, which mitigates DR5 expression and confers resistance to TRAIL in gliomas." (PMID 38802941, 2024). "The lack of relations between the possibility of CDC42EP3 upregulating and GFAP expression indicated that tumor-promoting effects mediated by CDC42EP3 overexpression may be independent of its regulation on coordinating actin and septin cytoskeleton rearrangements in glioma CAFs." (PMID 35365622, 2022). "Notably, GFAP expression is absent and vimentin expression is variable in C6 glioma cells." (PMID 33790744, 2021). "Thus the enhanced expression of GFAP, mortalin and NCAM in ASH-WEX-treated cells, in the present study, may suggest the possible mechanism(s) of differentiation inducing potential of Ashwagandha for the treatment of gliomas." (PMID 20007262, 2011). "On the one hand, this effect in the long term may be unfavorable as GFAP-negative cells have been shown to have a higher average number of nucleolar organizer regions (Ag-NOR), an increase in which has been linked in a couple of papers to a worse prognosis in several cancers, including gliomas." (PMID 39201395, 2024). "The IDH1 mutation impeded the maturation of astrocytes with low OGDH, but we found that it did not alter the expression of GFAP, Nestin, CD133, and CD44 in U87 and U251 glioma cells." (PMID 39872214, 2024). "Some existing molecular biomarkers, such as GFAP, IDH1 and Ki-67 antigen, are helpful for the diagnosis of molecular subtypes, individualized treatment and clinical prognosis of glioma, but their sensitivity and accuracy are still lacking." (PMID 37602882, 2023). "Conversely, we detected that low grade gliomas (LGG) exhibited homogenous round cells, GFAP+, and IBA1+ cells throughout the tumor with no defined orientation or alignment." (PMID 35750880, 2022). "iNHAs overexpressing CCDC88A-ALK or PPP1CB-ALK were tumorigenic in vivo with 100% penetrance, forming glial tumors with a high MIB-1 proliferative index, pseudopalisading necrosis, focal GFAP expression, lack of synaptophysin expression and ALK overexpression." (PMID 31554817, 2019). "In glioma patients, baseline CD9+/GFAP+/SVN+ exosome levels had no apparent correlation with percentage of survivin-positive cells detected in tumor tissue by immunohistochemistry." (PMID 29383115, 2017). "Across the range of neural tumors, GFAP, OLIG-2 and MAP-2 are generally expressed by gliomas, while the neuronal marker synaptophysin is not." (PMID 25955030, 2015). "Overall, 110 genes were upregulated in both cell lines after 200 nM DAC treatment, and upregulation of GFAP and other glial differentiation markers was not evident in TS667 glioma cells." (PMID 24077826, 2013). "Irrespective of the grade and morphological diagnosis of gliomas, glioma cells concomitantly expressed PDGFRα, A2B5, O4, CD44 and GFAP." (PMID 18398462, 2008). "They displayed a typical protoplasmic morphology, being strictly GFAP positive and never co-labelled with βIII-tubulin – the latter phenomenon having recently been documented in transformed NSC-like glioma cells." (PMID 18836552, 2008). "In low-grade gliomas, no obvious expression of NSE and synaptophysin was detected, but the cells homogeneously expressed GFAP." (PMID 18398462, 2008). "However, GFAP, SOX10, CD24, EMA, CKAE1/3, and PR negativity rule out meningiomas, glial tumors, schwannomas, metastatic melanomas or carcinomas." (PMID 41302074, 2025). "Importantly, the morphological aspect and lack of immunoreactivity for GFAP and SMA within the tumor itself helps rule out gliomas, meningiomas, or smooth muscle tumors as differential diagnoses." (PMID 41203869, 2025).